CYP3A4 (cytochrome P450 family 3 subfamily A member 4)
Diseases named in the same sentence as CYP3A4 in open-access papers (continued):
Sharing a sentence is not in itself a finding about the gene and the disease.
cancer (continued). "We, therefore, examined the involvement of JNK and ERK in the expression levels of CEBPB and CYP3A4 in cancer spheroid models." (PMID 37958656, 2023). "The phosphorylation levels of Akt were significantly reduced by inhibiting KCa1.1 in cancer spheroid models, and KCa1.1-induced down-regulation of CYP3A4 was reversed by the treatment with Akt and Nrf2 activators." (PMID 37958656, 2023). "DOX is one of the most widely used drugs in chemotherapy for the treatment of different types of cancers and is a major substrate of CYP3A4-mediated oxidation." (PMID 37958656, 2023). "The predicted inhibition with these Ni2+ and Cu2+ complexes indicates that CYP3A4 overexpression in a diseased state like cancer would reduce, thereby increasing the chemotherapeutic compounds' shelf-lives for adsorption." (PMID 37591990, 2023). "In TME, an increase in CYP3A4 metabolic activity plays an important role in the acquisition of chemoresistance by cancer cells." (PMID 37958656, 2023). "This induction effect of CYP3A2 (CYP3A4 in humans), a detoxifying enzyme, has been found for anti-cancer chemotherapy drugs such as docetaxel, vincristine, and paclitaxel." (PMID 37259384, 2023). "DOX resistance was overcome by the siRNA-mediated inhibition of CYP3A4 and treatment with the potent CYP3A4 inhibitor, ketoconazole, in cancer spheroid models." (PMID 37958656, 2023). "Higher CYP3A4 expression is generally noted in cancer cells compared to normal tissues as well as in primary tumors of distant metastatic patients compared to non-metastatic patients." (PMID 36613834, 2022). "In patients experiencing cancer progression, the expression and activity of CYP3A4 is significantly lower, which can be explained by a greater plasma concentration of inflammation mediators, in particular, IL-6." (PMID 36359206, 2022). "L-02 cells are normal human hepatocytes that also exhibit CYP1A2 and CYP3A4 expression and can be used as control cells to compare to cancer cells." (PMID 34031539, 2021). "Genetic variation in CYP3A4 and CYP2B6 have previously been associated with gonadotoxicity after cancer treatment." (PMID 34572825, 2021). "After long-term use, cabozantinib would be expelled out of the cancer cells and contribute to the development of resistance when the expressions of CYP3A4 and multidrug resistance protein 2 increased." (PMID 34722310, 2021). "Prior work has shown increases in circulating C-reactive protein (CRP) inflammatory cytokine, correlate to decreased CYP3A4 activity in advanced cancer patients." (PMID 33707475, 2021). "This work further confirms the upregulated metabolic expression of CYP3A4 decreases doxorubicin efficacy in confirmation with previous studies across multiple cancer types, including liver, colorectal, breast, and prostate." (PMID 34262860, 2021). "The CYP3A4 enzyme is one of the major mechanisms of drug metabolism for cancer therapeutics, including sorafenib and doxorubicin, in the liver." (PMID 34262860, 2021). "The increased circulating CRP and IL-6 along with reduced CYP3A4 activity observed in a subset of cancer patients indicates the role of IL-6 as being a potential mediator in the process." (PMID 33076284, 2020). "P-gp and CYP3A4 are overexpressed in a number of different cancers such as ovarian, breast, and colon cancers, and some studies showed that they are associated with resistance to therapy and/or poor prognosis." (PMID 33053111, 2020). "Intriguingly, van Erp and co-authors (2005) investigated the effects of milk thistle extract (200 mg containing 80% silymarin, thrice daily) in six cancer patients on the pharmacokinetics of irinotecan, substrate for CYP3A4 and UGT1A1." (PMID 32635538, 2020). "Anti-cancer treatments predicted to affect direct oral anticoagulant plasma levels through moderate to strong interaction with CYP3A4 or P-glycoprotein or both." (PMID 31297188, 2019).
cancer (continued). "The influence of St John's wort on the pharmacokinetics of docetaxel, a CYP3A4 substrate, was evaluated in 10 cancer patients." (PMID 31850232, 2019). "In cancer cells, PGRMC1 facilitates the degradation of the chemotherapeutic agent doxorubicin by activating CYP2D6 or CYP3A4, leading to a reduction of the anti-cancer effect of doxorubicin." (PMID 30087538, 2018). "It has been reported that several anti-cancer agents such as tamoxifen can induce CYP3A4 in cancer cells, which is related to the acquisition of chemoresistance." (PMID 29050342, 2017). "CYP3A4, measured by immnuohistochemistry in normal and cancer breast tissue biopsies was found to be prognostic for patient response to docetaxel 35, 36 and by activity assay and western blot to correlate with ifosfamide activation." (PMID 28488344, 2017). "First, inter-individual variability in CYP3A4 expression is a confounding factor during cancer treatment." (PMID 26901218, 2016). "In the current paper, we examined the effects of lansoprazole and omeprazole enantiomers on the expression of key drug-metabolizing enzyme CYP3A4 in human hepatocytes and human cancer cell lines." (PMID 25141173, 2014). "In the current paper we examined the effects of lansoprazole and omeprazole enantiomers on the expression of CYP3A4 in human hepatocytes and human cancer cell lines, and on transcriptional activity of PXR and GR in transgenic cell lines." (PMID 25141173, 2014). "This does not seem to be the case, thus rendering higher concentrations of nemorosone for cancer treatment preferable over those of hyperforin for which multiple drug interactions related to CYP3A4 induction have been reported." (PMID 24040280, 2013). "More recently, the presence of a systemic inflammatory response has been shown to impair the activity of cytochrome 3A (CYP3A4) in patients with advanced cancer patients." (PMID 22433965, 2012). "In this work we demonstrated that a biosensor based on cytochrome P450 (CYP1A2, CYP2B6 and CYP3A4) and carbon-nanotubes enable the identification of different anti-cancer drugs, thus providing an innovative solution for point-of-care drug monitoring." (PMID 22778656, 2012). "Since, Curcuma drugs suppressed activity and expression of CYP3A4 in intestinal epithelial cells, our observation that GLT down-regulates PhiP/DSS-dependent expression of CYP3A4 in vivo, further confirms cancer preventative activities of GLT." (PMID 23118901, 2012). "In a cell-based screen designed to identify compounds that activate PXR-mediated CYP3A4 gene expression in HepG2 human carcinoma cells, we identified several flavonoids, such as luteolin and apigenin, as PXR activators." (PMID 20553580, 2010). "This concept is supported by data which demonstrated that reductions in CYP3A4 activity in patients with advanced cancer were correlated with increased plasma concentrations of IL-6 and CRP." (PMID 19450285, 2009). "Previous studies have demonstrated that the activity of a different enzyme, CYP3A4, is also decreased in advanced cancer patients and that the decreased activity correlates with inflammatory response." (PMID 18854824, 2008). "By turn, the presence of CYP3A activity would confer to cancer cells the ability to inactivate two widely used taxanes, such as paclitaxel and docetaxel and vinca alkaloids that are CYP3A4 substrates." (PMID 12237780, 2002). "The researches on CYP3A4 expression in cancer are mainly focused on drug resistance." (PMID 40630116, 2025). "The pathway is a known mediator of fibrosis and suppressor of vascular invasion via cancer-associated fibroblasts (CAFs), potentially providing this subgroup with a more immunoprotected microenvironment.CYP2B6, CYP1A2, and CYP3A4 were associated with the “Chemical carcinogenesis” pathway." (PMID 40349011, 2025).
cancer (continued). "Inhibiting CDK9 disrupts transcriptional processes crucial for cancer cell survival and proliferation while modulating CYP3A4 activity could optimize the pharmacokinetics of chemotherapeutic agents, improving their efficacy." (PMID 39498375, 2024). "Compared with other coumarins, bergaptol has the least potency to inhibit CYP3A4 in cancer cells." (PMID 38338457, 2024). "In cancer, CYP3A4 can affect the efficacy of chemotherapy by metabolizing anticancer drugs, which may lead to drug resistance." (PMID 39498375, 2024). "Of note, this is the first DDI study using this moderate CYP3A4 inducer in cancer patients." (PMID 38399397, 2024). "In addition, CYP2D6, CYP3A4, CYP2B6, and CYP2C19 are implicated in anti-cancer metabolism, influencing their efficacy." (PMID 39062040, 2024). "Although CDK9 and CYP3A4 perform distinct biological functions, targeting both could yield synergistic effects in cancer treatment." (PMID 39498375, 2024). "Inflammation and cancer have been shown to increase inflammatory markers that may affect CYP3A4 gene expression." (PMID 38882983, 2024). "Therefore, concurrent use of St John’s wort and anti-cancer agents that are substrates of CYP3A4 and/or ABCB1 can result in a clinically significant pharmacokinetic interaction and unwanted therapeutic outcome." (PMID 36707434, 2023). "Furthermore, a meta-analysis of oral clearance values in healthy volunteers versus cancer patients showed similar elimination across several CYP3A4 substrates, including imatinib, everolimus, ibrutinib, midazolam, dastanib and nilotinib." (PMID 37514108, 2023). "An in vitro analysis of human liver microsomes has revealed the ability of CYP3A4 to inactivate other active forms of vitamin D, its 20(OH)D3 derivative, and other relevant metabolites that may also have a physiological effect on cancer cell proliferation." (PMID 36359206, 2022). "The results significantly demonstrated that both of two compounds may be developed to CYP3A4 or 2C19 target new drugs, and combination with other cancer drugs in clinical practice." (PMID 35889364, 2022). "Moreover, quercetin nanoparticles can positively affect the bioavailability of other drugs, like doxorubicin, a cytotoxic drug used in cancer treatment that has poor oral solubility but increases its bioavailability when CYP3A4 and P-gp are inhibited." (PMID 35628203, 2022). "Part of the unexplained variability may be attributable to variability across patients in CYP3A4 activity, the hypothesized primary route of berzosertib elimination, and is consistent with previous studies in cancer patients." (PMID 33145616, 2021). "Since we are not aware of any cases where docetaxel was safely given to cancer patients with two reduced-function CYP3A4 alleles, we propose that extreme caution should be used when treating those patients with docetaxel." (PMID 35174070, 2021). "Mammary tumor engraftment is inhibited through the knockdown of cancer cell intrinsic CYP3A4." (PMID 31998435, 2020). "Therefore, lipid based formulation can be employed for lymphatic voyage of anti-cancer drugs with additional benefits of P-gp and CYP3A4 modulation for drugs having poor hydrophilicity, low intestinal permeation and high CYP3A4 mediated metabolic activity." (PMID 33072532, 2020). "Thus, a 49% decrease in docetaxel clearance was observed in patients with cancer treated with docetaxel in conjunction with the active CYP3A4 inhibitor ketoconazole." (PMID 31998435, 2020). "Consequently, co-administration of CCT241736 and CYP3A4 inhibitors (such as the azole antifungals often used prophylactically in cancer treatment) is therefore likely to be contraindicated." (PMID 30953752, 2019). "In a study in 10 cancer patients, echinacea did not cause significant alterations in the pharmacokinetics of docetaxel, which is a substrate of CYP3A4 and P-gp." (PMID 31850232, 2019). "CYP3A4 is also expressed in several cancer cell lines such as breast, colon and liver." (PMID 29050342, 2017).
cancer (continued). "In conclusion, the present data suggested that fucoxanthin inhibits CYP1A1, CYP1A2 and CYP3A4 enzyme activity and that these inhibitory effects may contribute towards the cancer preventive action of fucoxanthin." (PMID 24137426, 2013). "For example, expression differences in DMET genes such as CYP3A4, CYP2A6 and GSTA1 may be associated with cancer risks." (PMID 29177108, 2012). "Most cancer drugs are metabolized by CYP3A4, including those used to treat NHL." (PMID 19450285, 2009). "Therefore, in cancer patients receiving 25 mg i.v. temsirolimus, concomitant treatment with agents that have strong CYP3A4 inhibition potential should be avoided." (PMID 18458675, 2008). "However, the high number of drugs that are CYP3A4 substrates and the fact that cancer patients are often simultaneously treated with several drugs, makes it undesirable to cause a systemic inhibition of CYP3A4 in these patients." (PMID 12237780, 2002). "Our study aimed to examine whether the predominant pathway for oxycodone metabolism – CYP2D6 and CYP3A4 – metaboliser status affect oxycodone dose, pain scores, and adverse effects in an Australian patient population with pain from advanced cancer, a population which commonly requires oxycodone." (PMID 39628313, 2024). "Therefore, managing CYP3A4 activity is critical for effective cancer treatment." (PMID 39498375, 2024). "While the pregnancy model, implemented approximately a 100% increase in CYP3A4 expression and a 25% increase in renal function at 32 gestational weeks, both simulation results showed that the pregnancy model overestimated paclitaxel exposure (around 40% higher) in pregnant patients with cancer." (PMID 38140068, 2023). "When extrapolating to doses for patients with moderate to severe RI, in addition to accounting for physiological changes relating to the cancer itself (captured by the Sim-Cancer population), changes in CYP3A4 and potentially other CYP enzymes may need to be considered." (PMID 37514108, 2023). "Although the interaction of rifampin combined with famitinib in cancer patients in not clear, it is reasonable to assume that concomitant therapy with potent CYP3A4 inducer such as rifamipin may impair the therapeutic properties of famitinib in the treatment of malignant tumors." (PMID 36107220, 2022). "On the other hand, primary lung tissues were characterized by lower CYP3A4/5 and P-gp expression, while the cell line Calu-3 showed intermediate characteristics, with low CYP3A4 and high P-gp expression, in line with upregulation of the latter marker in cancer cells." (PMID 35229634, 2022). "The ability of CYP3A4 to catalyze the inactivation of 1,25(OH)2D3 and of other active forms of vitamin D has an influence on cancer cell proliferation and may be clinically important in various common cancers, mostly breast, prostate, and colorectal malignant tumors." (PMID 36359206, 2022). "Therefore, finding an efficient CYP3A4 inhibitor or multidrug resistance protein 2 inhibitor may improve the systematic exposure of cabozantinib in cancer therapy under the premise of ensuring the safety of patients." (PMID 34722310, 2021). "Therefore, in cancer patients concurrently treated with strong CYP3A4 inducers or inhibitors, dabigatran (or possibly edoxaban) may become the DOAC of choice; such decision-making may benefit from close collaboration with a clinical pharmacist." (PMID 31963461, 2020). "Other genes such as CYP3A4, CYP2C9, ADH4, ADH1A, and CYP1A2 enriched in the cytochrome P450 pathway are observed as metabolically active procarcinogens to genotoxic intermediates, and an association has been found between CYP enzyme activity and the risk to develop several forms of cancer." (PMID 31024618, 2019). "Together with the hypothesis that smoking leads to induction of CYP3A4 and that fentanyl metabolism might also be influenced by other (unknown) metabolic pathways it might be interesting to study smoking in a larger cohort of patients with cancer." (PMID 29883454, 2018).
cancer (continued). "The aim of these studies was to test if common patient variables, i) the use of the moderate CYP3A4 inhibitor aprepitant and ii) the localization of the fentanyl patch (upper arm versus thorax) influence systemic exposure to fentanyl in patients with cancer using a transdermal fentanyl patch." (PMID 29719604, 2018). "Both aprepitant and fentanyl are thus widely and simultaneously used in cancer patients and because of aprepitant's inhibitory capacity on CYP3A4, it could hypothetically increase the exposure of fentanyl, leading to more side effects like nausea or sleepiness." (PMID 29719604, 2018). "Thus, SFN as an antagonist of hPXR may reduce adverse therapeutic agent responses and enhance cancer chemoprevention via the repression of hPXR-regulated CYP3A4." (PMID 25364403, 2014). "Taken together, Uncaria tomentosa extract may be useful for cancer patients as a complementary and alternative medicine, making sure not to interfere with the well-established treatment protocols, as well as evaluating the possible CYP3A4 inhibition." (PMID 25505920, 2014). "Activation of the PI3K/AKT pathway contributes to multidrug resistance (via ABCG2), alters the drug metabolism (via CYP3A4), and enhances cell survival (via MCL1), all of which play key roles in cancer cell resistance to chemotherapy drugs like irinotecan." (PMID 39931465, 2025). "The ABCG2, CYP3A4, MCL1, and MLH1 genes are overexpressed in various cancers and are involved in chemoresistance to multiple drugs." (PMID 39931465, 2025). "Some examples of anti-cancer drugs metabolized by CYP enzymes include tamoxifen by CYP2D6, docetaxel and cyclophosphamide by CYP3A4/5, and paclitaxel by CYP2C8." (PMID 41009411, 2025). "The PI3K/AKT signaling pathway is a common molecular route that links the ABCG2, CYP3A4, and MCL1 genes, particularly in the contexts of cancer and drug resistance." (PMID 39931465, 2025). "In cancer cells, PXR ligands enhance PXR-mediated transcription in a ligand- and promoter-dependent manner, thereby leading to differential regulation of CYP3A4 and MDR1." (PMID 39682707, 2024). "TIMER database was used for pan‐cancer analysis of different pain genes (Nav1, EHMT2, SP1, SLC6A4, COMT, OPRM1, OPRD1, CYP2D6, and CYP3A4)." (PMID 38352696, 2024). "The differential expression of PIK3R1, AKR1C3, EGFR, ESR1, PIK3CD, CYP3A4, and CYP19A1 across various cancer types and stages illuminates their potential as biomarkers for cancer progression and prognosis." (PMID 39204124, 2024). "As many anticancer agents (and other drugs administered for conditions that frequently occur in patients with advanced cancer) are CYP3A4 substrates, capivasertib is likely to be administered concomitantly with CYP3A substrates in clinical practice." (PMID 38643311, 2024). "Consistent with the results obtained on the siRNA-mediated inhibition of CYP3A4, its pharmacological inhibition with the potent CYP3A4 inhibitor, ketoconazole (KCZ, 1 μM), significantly reversed DOX resistance in cancer spheroid models (n = 5, p < 0.01)." (PMID 37958656, 2023). "To elucidate the contribution of CYP3A4 and CYP2B6 to DOX resistance in the three cancer spheroid models, we examined the effects of their siRNA-mediated inhibition on DOX resistance." (PMID 37958656, 2023). "To elucidate the possible contribution of PP2A to the KCa1.1 inhibition-induced down-regulation of CYP3A4 in cancer spheroid models, we examined the effects of the PP2A activator, FTY720-P, on the expression level of CYP3A4 transcripts." (PMID 37958656, 2023). "The activation of PP2A by FTY720-P reduced the expression levels of the CYP3A4 and CEBPB in cancer spheroid models." (PMID 37958656, 2023). "The PBPK model helps reduce the number of clinical DDI studies needed to characterize CYP3A4-mediated DDI with ipatasertib and provides an ethical benefit for patients with cancer." (PMID 35428895, 2022).